SOX2 (SRY-box transcription factor 2)
Diseases named in the same sentence as SOX2 in open-access papers (continued):
Sharing a sentence is not in itself a finding about the gene and the disease.
infection (continued). "Moreover, we generated reprogrammable rats from riPSCs that were created by infection of three reprogramming factors (Oct3/4, Klf4, and Sox2) via an inducible lentiviral vector." (PMID 21789202, 2011). "We here show that infection with a lentiviral vector carrying three mouse reprogramming factors (Oct4, Klf4, and Sox2) and culture in the presence of two kinds of kinase inhibitors (MEK inhibitor and GSK3 inhibitor) permit efficient establishment and maintenance of riPSCs from REFs." (PMID 21789202, 2011). "At 24 h after infection, the Ad-SOX2-infected OUMS37 cells showed a higher proportion of cells in G1 phase (58.4%), compared with the control cells (41.6% for parental cells and Ad-GFP-infected cells), and concomitant decreases in the proportions of cells in S and G2/M phases." (PMID 18268498, 2008). "Co-immunostaining of 17syn+-infected organoids (day 3 post-infection) for pSer199/202 and the NPC marker SOX2 provided evidence of nuclear accumulation of phosphorylated tau in NPCs following HSV-1 infection." (PMID 39818277, 2025). "In KP and KPU tumors following Ad5-CC10-Cre infection, we classified subtypes of KP and KPU tumors by NKX2-1 and SOX2 expression levels." (PMID 38093367, 2023). "As Sox2 and Sox17 are both essential for early development, we conclude that ZIKVUG infection is detrimental to the ICM lineages." (PMID 35900100, 2022). "Together, these findings suggested that non-SOX2 cell autonomous (e.g., microenvironment) factors regulated ZIKV progenitor cell infection." (PMID 36174572, 2022). "Immunostaining of day 30 and day 60 brain organoids with SOX2+ NSCs and MAP2+ neurons showed a time-dependent increase of nucleoprotein (NP)+ cells compared to mock infection, especially for MAP2+ neurons." (PMID 35910807, 2022). "During the four days following the infection, the CD44, SOX2, NANOG, and OCT4 levels have changed significantly at p ≤ 0.001 with respect to duration of infection." (PMID 33093503, 2020). "H. pylori infection slightly decreased SOX2 expression in wild-type mice, while infected RNF43H292R/H295R mice showed markedly lower levels of SOX2 upon infection when compared to uninfected mutant mice." (PMID 30884828, 2019). "To evaluate the induction of tumorigenicity in HaCaT cells by OSKM-N factors, we obtained cells that stably expressed OCT4, SOX2, KLF4, C-MYC, or NANOG by infection with lentiviral particles after the selection period." (PMID 31885625, 2019). "Fibroblasts from the CLN5 patient were reprogrammed by the expression of SOX2, OCT3/4, KLF4 and MYC after infection with a Sendai virus delivery vector, in order to produce integration-free CLN5Y392X iPSCs." (PMID 28468312, 2017). "Ad-ATF/SOX2 dose dependently increased FLAG tagged ATF/SOX2 expression in EBC2 lung SCC cells, TE1 and TE4 esophageal SCC cells 48 hours after infection." (PMID 29262545, 2017). "Although ZIKV infected both Sox2+ and Sox2− cells, the majority of the remaining cells in ZIKV infected cultures after 72 h of infection were Sox2−." (PMID 28008958, 2016). "The cells were then used for generating iPS cells after infection with retroviruses containing human OCT3/4, SOX2, C-MYC and KLF4." (PMID 24577094, 2014). "Meanwhile, the expression of Sox2, Oct4 and Nanog in HeLa/TSA cells was reduced significantly after LV-UbBsi infection, and the SP+ ratio of HeLa/TSA-LV-UbBsi cells was significantly reduced from 2.58% to 1.25% (p<0.01)." (PMID 24367661, 2013). "Our results showed that the infection did not change the mRNA expression of SOX2, NANOG, and POU5F1, but increased the mRNA expression of TLR4 and the cell surface expression." (PMID 40573358, 2025). "The induction of Lgr5 was fairly specific, as other gastric stem cell markers, such as Sox2, Troy, Runx1, Lrig1, and others were not induced as a consequence of infection; an exception was Ascl2, the expression of which mirrored that of Lgr5." (PMID 39191487, 2024).
infection (continued). "Using SOX2+ GBM cell lines, we found that CD11b+ conditioned medium containing type 1 interferon beta (IFNβ) promoted progenitor resistance to ZIKV, whereas inhibition of JAK1/2 signaling restored productive infection." (PMID 36174572, 2022). "As discussed, the same impact on SOX2 expression was also noted after infection of similar cells with CMV and HSV, indicating that SOX2-related auditory development processes like axial specification of the otocyst and generation of the cochlear duct also can be affected by HIV." (PMID 33419104, 2021). "On average, neural progenitor Sox2-positive signal was unchanged regardless of infection or recombinant IFN treatment." (PMID 31739796, 2019). "These cells may be derived from another undefined cluster (C4) that has some SOX2 and VIM expression and also shows a modest proportional decrease in cell number with infection." (PMID 31739796, 2019). "FLAG-tagged ATF/SOX2 was not induced and SOX2 expression was not changed after Ad-null infection in the cells." (PMID 29262545, 2017). "By 36 hr post-Lenti-SOX2 infection of plastic basal cell cultures, most cells expressed SOX2 protein, as well as the basal cell marker TP63, but did not yet express markers of overt mucinous or squamous differentiation." (PMID 27880766, 2016). "We next tested whether a synchronized population could elevate the expression of reprogramming factors after OCT3/4, SOX2, C-MYC, and KLF4 infection." (PMID 22529890, 2012). "As controls, nontreated MEF were plated for infection with retrovirus for (i) mOct4 and Sox2 only, (ii) mOct4, mSox2 and mKlf4 only, or (iii) mOct4, mSox2, mKlf4, and mcMyc." (PMID 22619682, 2012). "In this system, primary iPS cells were generated first by infection of neonatal tail-tip fibroblasts, carrying the ROSA-rtTA transactivator, with lentiviruses expressing Oct4, Sox2, Klf4 and cMyc, each under the control of a doxycycline (dox)-inducible promoter." (PMID 22028872, 2011). "Although these cell lines showed basally low levels of SOX2 expression, abundant SOX2 protein was detected after Ad-SOX2 infection but not after the control Ad-GFP infection." (PMID 18268498, 2008). "We found striking differences in relative rates of infection between these explants that could not simply be accounted for by cell-intrisic factors such as SOX2 expression levels." (PMID 36174572, 2022). "Infection of human iPS cells with lentivirus expressing Cas9-sgRNA followed by puromycin selection for guide expression did not alter expression of key transcriptional markers of pluripotency, POU5F1, Nanog or Sox2 or iPS cell proliferation rate relative to uninfected cells." (PMID 34230586, 2021). "AAV8‐IL‐31, but not AAV8‐vector, infection also induced the development of POU2F2+ OCT4+, POU2F2+ SOX2+, and POU2F2+ NANOG+ hepatocytes at months 6 and 10 post‐DEN." (PMID 37733361, 2021). "We observed that WT- and NPC-iNSCs showed no detectable expression of retroviral specific SOX2 and HMGA2, whereas WT- and NPC-hDFs on day 5 after infection exhibited high expression levels, suggesting that exogenous factors were silenced in both WT- and NPC-iNSCs." (PMID 29156730, 2017). "First, pig iPSCs could be induced by KLF4, SOX2, and MYC (but not OCT4) infection, although transgenes were not silenced." (PMID 27336671, 2016). "Interestingly, despite higher productive infection in HDB samples, the proportion of SOX2+ cells was higher in MR GBM than in HDB, indicating that the SOX2+ composition alone could not account for differential vulnerability in HDB versus GBM." (PMID 36174572, 2022).
adenocarcinoma (63 papers, 2010 to 2025). A common cancer characterized by the presence of malignant glandular cells. "Instead, we observed that the mutation of KMT2D and CNV amplification of SOX2 were significantly associated with high adenocarcinoma/squamous ratios." (PMID 37051524, 2023). "Notably, the poor survival associated with SOX2 expression that was reported in GI tract cancer mostly pertained to adenocarcinoma." (PMID 26706028, 2015). "Finally, the Adenocarcinoma factor shows association with the RNA expression of a number of keratins, negative coefficients for both copy number and RNA expression of SOX2 and positive association with both RNA expression and copy number of NKX2-1 (also known as TTF1)." (PMID 30379847, 2018). "SOX2 is overexpressed in human squamous cell lung tumors and in some adenocarcinomas, where it is proposed to play different roles." (PMID 39272828, 2024). "The CDX2 and SOX2 expression demonstrated a converse pattern in the metaplasia-dysplasia-adenocarcinoma progression sequence in both esophageal and gastric cases." (PMID 36994101, 2023). "Our study is the only one so far to evaluate the correlation of the markers ALDH1, BMI-1, CD44, Nanog, and SOX2 with survival-rates and clinicopathological data in adenocarcinoma of the major salivary glands." (PMID 33009929, 2021). "Most of the adenocarcinomas were mainly Sox2-negative but some were completely or partially Sox2-positive." (PMID 31208373, 2019). "Sox2 staining of lung sections of adenocarcinomas and bronchioles from control and Nanos3 NSCLC mice." (PMID 31208373, 2019). "In our TNBC model, we found up-regulation of Pou5F1 (Oct-3/4), Kit, Cd24 and Itga6 (Cd49f) in epithelial-like adenocarcinoma areas of primary tumors, while Klf4, Sox2, Cripto-1 were expressed in the mesenchymal/EMT-like regions." (PMID 26059540, 2015). "Multivariate analysis of overall survival indicated increased SOX2 gene copy number (P = 0.008), stage I-II (P<0.001), and adenocarcinoma or SCC histology (P = 0.016) as independent, favorable prognostic factors." (PMID 24736592, 2014). "Overall, Sox2 was expressed in all stages of adenocarcinoma and its levels were significantly higher in metastatic lesions." (PMID 23009336, 2012). "Lu reported that SOX2 was over-expressed in human squamous cell lung tumors and some adenocarcinomas." (PMID 21982273, 2011). "Nuclear SOX2 levels were largely and statistically significantly higher in lung SCCs (n = 109, set I; n = 177 set II) relative to the levels in adenocarcinomas (set I, n = 178; set II, n = 334) (both p<0.001)." (PMID 20161759, 2010). "In our model, Sox2 overexpression in Scgb1a1-positive cells drives development of histologically well differentiated adenocarcinoma with significant squamous cell features including widespread expression of p63, FoxE1 and Desmoglein3." (PMID 20548776, 2010). "Given the effective separation of lung SCCs and adenocarcinomas by this signature, it is possible that other genes directly or indirectly related to SOX2 signaling are also dissimilar in expression between both NSCLC subtypes." (PMID 20161759, 2010). "Here, we found that SOX2 mRNA levels, from various published datasets, were significantly elevated in lung SCCs compared to adenocarcinomas (all p<0.001)." (PMID 20161759, 2010). "In this study, we found that SOX2 mRNA was largely higher in lung SCCs relative to adenocarcinomas from various microarray datasets." (PMID 20161759, 2010). "Developmental models demonstrate roles for mutant KRAS in the establishment of AT2 cell adenocarcinomas dependent on SOX2 and Notch temporal expression levels and both SOX2 and SOX9 can promote cellular trans-differentiation via epithelial mesenchymal transition (EMT)." (PMID 31581742, 2019). "In contrast to SCCs, adenocarcinoma samples had significantly lower expression of Sox2." (PMID 23009336, 2012).
adenocarcinoma (continued). "There was a positive correlation between SOX2 and the pathological degree of human adenocarcinoma (p = 0.002), indicating that SOX2 may inhibit the differentiation of adenocarcinoma cells." (PMID 22615765, 2012). "We show that SOX2 is overexpressed in human squamous cell lung tumors and some adenocarcinomas." (PMID 20548776, 2010). "In addition, SOX2 expression in the cluster analyses was higher in lung SCCs relative to adenocarcinomas." (PMID 20161759, 2010). "Moreover, a previously characterized OCT4/SOX2/NANOG signature effectively separated lung SCCs from adenocarcinomas in two independent publicly available datasets which correlated with increased SOX2 mRNA in SCCs." (PMID 20161759, 2010). "Moreover, SOX2 protein expression was greatly higher in lung SCCs compared to adenocarcinomas following analyses in two independent large TMA sets (TMA set I, n = 287; TMA set II, n = 511 both p<0.001)." (PMID 20161759, 2010). "It is plausible to suggest that the reduction in SOX2 expression in adenocarcinomas of the lung may be evolutionarily conserved." (PMID 20161759, 2010). "Lastly, we demonstrated that SOX2 protein expression was largely significantly elevated in lung SCCs relative to adenocarcinomas following analyses of two independent TMA sets and copy gain of the gene was evident in 20% of lung SCCs studied and absent in adenocarcinomas." (PMID 20161759, 2010). "By contrast, 4/20 adenocarcinoma samples stained positively for SOX2." (PMID 20548776, 2010). "SOX2 may induce a stem-like transcriptional program and has been demonstrated to be upregulated in poorly-differentiated adenocarcinomas by genomic analyses." (PMID 20548776, 2010). "Analysis of SOX2 mRNA expression in NSCLC samples of various publicly available datasets revealed the significant elevated expression of this stem cell-related transcriptional factor in lung SCCs compared to adenocarcinomas (all p<0.001)." (PMID 20161759, 2010). "Notably, the median level of SOX2 protein was 8.2 and 39.7 higher in lung SCCs relative to adenocarcinomas when analyzed in TMA sets I and II, respectively (set I, adenocarcinoma, 30, SCC, 245; set II, adenocarcinoma 5.8, SCC, 230)." (PMID 20161759, 2010). "Specifically, the pre-castrated LTL-331 PDX initially exhibited a classic adenocarcinoma phenotype and gradually transformed to the t-NEPC LTL-331R PDX after surgical castration, during the process EHF was notably depressed and positively associated with AR, and negatively with SYP and SOX2." (PMID 33414441, 2021). "In addition, SOX2 is expressed in a small subset of adenocarcinomas." (PMID 20548776, 2010). "Modeling the therapeutic intervention of a SOX2 degrader as a delayed degradation reaction, AST is effectively blocked and reprogrammed back to the adenocarcinoma state, providing a useful clue for targeting drug-resistant AST in the future." (PMID 40198732, 2025). "In vitro cell model studies have shown that SOX2 activates lysine-specific demethylase 1 (LSD1), significantly inhibiting the expression of adenocarcinoma-specific genes through epigenetic regulation, while mildly inducing the expression of certain NE markers." (PMID 40821114, 2025). "KPU tumors exhibited strong expression of squamous markers (SOX2 and CK5), while adenocarcinoma markers were dramatically downregulated." (PMID 38093367, 2023). "The RT-PCR data from our patients revealed more SOX2 and NANOG expression in ALDHhigh cells than in ALDHlow cells in adenocarcinoma." (PMID 31921651, 2019). "Gene amplifications of 3q including SOX2, TP63, PIK3CA, and EPHB3 were observed in as many as 86% of SQC samples but only 21% of adenocarcinoma samples." (PMID 28591695, 2017). "Here, we sought to characterize the expression profile of SOX2 and CDX2 in the sequential alterations of the esophageal mucosa towards adenocarcinoma and compare it with the well-established gastric and intestinal mucin profiles (MUC5AC, MUC6, and MUC2)." (PMID 27766003, 2016).
adenocarcinoma (continued). "Liu et al100 demonstrated that during the transition from adenocarcinoma to undifferentiated small-cell carcinoma, POU5F1, lin-28 homolog A (LIN28A), SOX2, and NANOG are sequentially activated, driving the transformation of differentiated adenocarcinoma to undifferentiated small-cell carcinoma." (PMID 40821114, 2025). "Regarding the results of our study and the literature, the CSCs ALDH1, BMI-1, CD44, Nanog, and SOX2 seem not to serve as reliable prognostic parameters in adenocarcinomas of the salivary glands." (PMID 33009929, 2021). "Recapitulating the results of our study in conjunction with the literature, the CSCs ALDH1, BMI-1, CD44, Nanog, and SOX2 do not seem to serve as reliable novel prognostic parameters in the treatment of adenocarcinoma of the salivary glands." (PMID 33009929, 2021). "Recapitulating the results of our study in conjunction with data in the literature, the CSCs ALDH1, BMI-1, CD44, Nanog, and SOX2 do not seem to serve as reliable prognostic parameters in the treatment of adenocarcinoma of the salivary glands." (PMID 33009929, 2021). "To explore how CCAT1 was regulated by TP63 and SOX2, we analyzed ChIP-seq data of H3K27ac, TP63, and SOX2 generated from SCC cells, and compared them to those from other cells types, including embryonic stem cells and adenocarcinoma cells from various organs." (PMID 30190462, 2018). "Our results as well as an earlier report suggest that Sox2 is expressed in both low as well as high stage adenocarcinomas irrespective of their grades." (PMID 23009336, 2012). "No adenocarcinoma stained positively for both SOX2 and p63, although others have demonstrated Sox2+/p63+ staining in up to 12% of human adenocarcinomas." (PMID 20548776, 2010). "Lastly, amplification of SOX2 DNA assessed by quantitative PCR (qPCR) was evident in 20% of lung SCCs studied (n = 40) and was absent in all adenocarcinoma cases tested (n = 17)." (PMID 20161759, 2010). "In contrast, none of the 17 adenocarcinomas tested displayed SOX2 gene copy gain with most cases (83%) exhibiting SOX2 DNA RQs<1." (PMID 20161759, 2010). "To determine whether USP13 can alter the lineage characteristics of advanced lung tumors through MYC, we overexpressed USP13 in the murine adenocarcinoma KP primary cell line and human LUAD cell lines followed by immunoblotting for squamous markers, such as SOX2, p40, or CK5." (PMID 38093367, 2023). "Furthermore, amplification of SOX2 DNA was detected in 20% of lung SCCs tested (n = 40) and in none of the adenocarcinomas (n = 17)." (PMID 20161759, 2010). "Moreover, SOX2 is highly (5.9-fold) overexpressed in squamous tumors when compared with adenocarcinomas (p<.0001, data not shown)." (PMID 20548776, 2010). "Expression heterogeneity was also found among LuCaP adenocarcinoma lines regarding the scTF genes – many with POU5F1, a few with LIN28A, none with SOX2 and NANOG." (PMID 31146720, 2019). "Although both components were NKX2-1-negative, markers of gastric differentiation were restricted to the adenocarcinoma component, and markers of squamous differentiation (including ΔNp63 and cytokeratins 5 and 14 (CK5 and CK14), but not SOX2) were selectively expressed in the SCC component." (PMID 30475207, 2018).
lung (11 papers, 2010 to 2023). "In fact, approximately 4% of the genes comprising the lung SCC signatures are known SOX2 targets in hESCs." (PMID 20126410, 2010). "We compared this list of known SOX2 targets to the lung SCC signatures and found significant overlaps." (PMID 20126410, 2010). "For example, SOX2 over-expression was recently reported to beassociated with better outcome in SCC, but with poor outcome in early stage lung ADC." (PMID 23990933, 2013).
CNS tumors (5 papers, 2012 to 2025). "The expression and requirement of SOX2 in central nervous system tumors is not surprising, given that SOX2 is expressed in neural progenitor cells and their progeny." (PMID 22937156, 2012). "The neural stem cell markers SOX2 and Nestin were also either not differentially expressed or under-expressed in the PLAGL-amplified type compared to the other CNS tumor types." (PMID 36437415, 2023).